CCL8 (C-C motif chemokine ligand 8)
Diseases named in the same sentence as CCL8 in open-access papers (continued):
Sharing a sentence is not in itself a finding about the gene and the disease.
latent infection (2 papers, 2014 to 2021). "Taking the data together, we show that the previously observed downregulation of hsa-miR-92a and upregulation of CCL8 during HCMV latent infection of myeloid cells are intimately linked via the latency-associated expression of LAcmvIL-10." (PMID 25253336, 2014). "We have analyzed the effect of HCMV latent infection on the secretome of CD14+ monocytes, identifying an upregulation of both CCL8 and CXCL10 chemokines in the CD14+ latency-associated secretome." (PMID 33912186, 2021). "Here, we have shown that experimental latent infection of CD14+ monocytes, an established in vitro model system for latent infection in vivo, also results in changes to the cellular secretome causing upregulation of cIL-10, CCL8 and, in particular, CXCL10." (PMID 33912186, 2021). "We have analyzed the functions of LAcmvIL-10 during latent infection of primary myeloid progenitor cells and found that LAcmvIL-10 is responsible, at least in part, for the known increase in secretion of cellular IL-10 and CCL8 in the secretomes of latently infected cells." (PMID 25253336, 2014).
liver disease (2 papers, 2012 to 2022). "Although no published studies have shown the specific role of CCL8 in liver disease, combined with the essential role CCL8 plays in other inflammatory diseases and tumor processes suggests that CCL8 may be involved in hepatitis virus infection, liver inflammation, steatosis, or fibrosis." (PMID 35281057, 2022). "These chemokines such as CCL2, CCL7, CCL8, CCL11 and CCL12 were demonstrated as pro-fibrosis cytokines in liver diseases and highly expressed during our murine schistosomiasis model, and reduced more or less after PZQ treatment." (PMID 22905138, 2012). "Although a variety of chemokines have been well studied in various diseases, there is no comprehensive review presenting the roles of all known chemokine ligands of CCR2 (CCL2, CCL7, CCL8, CCL12, CCL13, CCL16, and PSMP) in liver disease, and this review aims to fill this gap." (PMID 35281057, 2022). "However, other ligands of CCR2 have not been thoroughly studied in liver diseases, especially CCL7, CCL8, CCL12, CCL13, CCL16, and PSMP." (PMID 35281057, 2022).
mastitis (2 papers, 2016 to 2025). Inflammation of breast tissue during lactation or postpartum due to an obstructed duct or infection. "Results from previous studies indicated that bovine mammary epithelial cells can express CXCL6 (also called GCP2) and CCL8 (also called MCP2) in response to certain bacterial cell components during the simulation course of mastitis in vitro." (PMID 27478614, 2016). "Notably, the study underscores the roles of chemokines CCL8, CCL2, and CXCL10 in immune cell recruitment during mastitis, where their downregulation suggests impaired mammary immune defense that governs Chemokine signalling pathways." (PMID 40196120, 2025).
metabolic syndrome (2 papers, 2018 to 2025). A cluster of metabolic risk factors for CARDIOVASCULAR DISEASES and TYPE 2 DIABETES MELLITUS. "Conversely, the upregulation of proteins such as HGF and CCL19, along with increased inflammatory cytokines like IL-6, CXCL10, and CCL8, suggests an inflammatory environment that could predispose OBO individuals to the development of a metabolic syndrome." (PMID 40076884, 2025).
multiple sclerosis (2 papers, 2005 to 2017). A progressive autoimmune disorder affecting the central nervous system resulting in demyelination. "Complementing the genetic associations, we also detected a distinct regional expression regulation for CCL2, CCL7 and CCL8 in correlation with chronic inflammation in multiple sclerosis brains." (PMID 15730561, 2005). "In experimental multiple sclerosis mouse model, gal3−/− mice infected with Theiler’s murine encephalomyelitis virus have reduced CCL2, CCL5, CCL8, and CXCL10 expression and lower number of infiltrating cells in the brain subventricular zone." (PMID 28217127, 2017).
myocarditis (2 papers, 2024 to 2025). Myocarditis is a condition that is characterized by inflammation of the heart muscle (myocardium). "This peptide inhibits the inflammatory chemokines CCL2, CCL3, CCL7, and CCL8 in murine Coxsackievirus B3 (CVB3) infection, a viral trigger of myocarditis." (PMID 40009121, 2025).
neuropathy (2 papers, 2022 to 2023). A disorder affecting the nervous system that manifests with pain, tingling, numbness, and/or muscle weakness. "Among them, CCL7 and CCL8 are the common ligands of both receptors with well-known long-lasting increases and strong pronociceptive properties in neuropathy." (PMID 37570736, 2023). "Based on these data, we suggest that CCL8 may be one of the most important chemokines in neuropathy development, especially because it is also known that inhibition of CCL8 may decrease visceral hyperalgesia; however, more studies are needed to investigate its exact role in nociception." (PMID 36611891, 2022).
pancreatic ductal adenocarcinoma (2 papers, 2021 to 2023). An infiltrating adenocarcinoma that arises from the epithelial cells of the pancreas. "In pancreatic ductal adenocarcinoma, CCL8 promoted the proliferation and invasiveness of cancer cells through the NF-κB signaling pathway." (PMID 38136340, 2023).
sarcoidosis (2 papers, 2015 to 2017). Sarcoidosis is a multisystemic disorder of unknown cause characterized by the formation of immune granulomas in involved organs. "When comparing to control subjects, the expression levels of CC chemokines CCL3 (P = 0.043), CCL4 (P = 0.034), CCL5 (P < 0.001), and CCL8 (P = 0.031) and CXC chemokines CXCL9 (P < 0.001), CXCL10 (P = 0.002), and CXCL11 (P = 0.008) were found to be elevated in sarcoidosis patients." (PMID 26696750, 2015). "The CCL8 concentrations in BAL fluid was significantly higher in 86 patients with IPF than those in 41 controls, and other interstitial lung diseases including non-specific interstitial pneumonia (n = 22), hypersensitivity pneumonitis (n = 20) and sarcoidosis (n = 19) (p < 0.005, respectively)." (PMID 28057004, 2017).
sarcoma (2 papers, 2021 to 2022). A usually aggressive malignant neoplasm of the soft tissue or bone. "Despite most studies focusing on epithelial tumors, little is known about the role of CCL8 on macrophages in sarcoma." (PMID 36072582, 2022).
skin inflammation (2 papers, 2018 to 2019). "The miRNA precursor miR-146a can inhibit chronic skin inflammation by decreasing the expression levels of IFN-γ, CCL5, and CCL8 in the skin." (PMID 30459600, 2018). "As well as highlighting that Hh-mediated transcription in T cells promotes TGF-β signaling to dampen skin inflammation, our RNA-seq of CD4+ T cells from AD skin showed that Hh reduced expression of Ccl24 and Ccl8, and these chemokines recruit eosinophils to the skin." (PMID 31264977, 2019).
tuberculosis (2 papers, 2013 to 2020). A chronic, recurrent infection caused by the bacterium Mycobacterium tuberculosis. "In parallel, the monocyte-attracting chemokines CCL2, CCL8, and CCL7, associated with septic shock and tuberculosis, were elevated supporting the role of monocytes in disease pathogenesis." (PMID 33239683, 2020).
viral meningitis (2 papers, 2017 to 2019). Inflammation of the membranes surrounding the brain and spinal cord due to a viral infection. "Increased CSF levels of CCL8 have been found in undefined viral meningitis, in pneumococcal meningitis, and in neuroborreliosis, but not in Listeria monocytogenes meningitis." (PMID 28693588, 2017). "The chemokines CCL3, CCL7, CCL8, and CXCL9 were all significantly elevated in patients with LNB and bacterial and viral meningitis." (PMID 31727097, 2019).
vitiligo (2 papers, 2023 to 2024). Generalized well circumscribed patches of leukoderma that are generally distributed over symmetric body locations and is due to autoimmune destruction of melanocytes. "Meanwhile, recent evidence suggests that type 2 cytokines such as CCL2 and CCL8 are pivotal in shaping the vitiligo microenvironment." (PMID 38545113, 2024). "An in vitro experiment demonstrated that IFN-γ stimulation increased the expression of CCL2 and CCL8 by activating the JAK-STAT pathway in vitiligo fibroblasts." (PMID 38545113, 2024). "RNA sequencing revealed elevated chemokine CCL2 and CCL8 in vitiligo fibroblast, which may be regulated by the JAK-STAT signaling." (PMID 36672151, 2023). "As the IFN-γ stimulated vitiligo fibroblasts displayed a T cell-regulatory transcription profile, we suspected that CCL2 and CCL8 might function through reshaping the T cell landscape." (PMID 36672151, 2023). "Indeed, in total, our data demonstrated that IFN-γ in the vitiligo lesions stimulates fibroblast’s expression of CCL2 and CCL8 through activating the JAK2/STAT1 signaling pathway." (PMID 36672151, 2023).
acute myeloid leukemia (1 paper, 2020). Acute myeloid leukemia (AML) is a group of neoplasms arising from precursor cells committed to the myeloid cell-line differentiation. "In addition, a study on acute myeloid leukemia cells showed that chronic hypoxia increases CCL8/MCP-2 release." (PMID 32781743, 2020).
acute respiratory distress syndrome (1 paper, 2025). Progressive and life-threatening pulmonary distress in the absence of an underlying pulmonary condition, usually following major trauma or surgery. "More recently, a role for CCL8 has been proposed for the development of acute respiratory distress syndrome (ARDS) after SARS‐CoV‐2 infection, while the beneficial effects of CCL8 inhibition have been described following lipopolysaccharide administration in mice." (PMID 40545574, 2025).
adenoma (1 paper, 2021). A neoplasm arising from the epithelium. "Both the fold change in expression of CCL2, CCL7, and CCL8 and gene expression in adenoma were inversely correlated with a cumulative risk of transformation." (PMID 34884259, 2021). "The fold change in CCL2, CCL7, and CCL8 expression decreased gradually along with an increasing villous component in the adenomas." (PMID 34884259, 2021). "CCL2, CCL7 and CCL8 expression tended to decrease in the polyps compared with the normal tissue, though more markedly in the case of adenomas with high-grade dysplasia." (PMID 34884259, 2021). "CCL8 expression decreased along with an increasing villous component and was lower in adenomas with high-grade dysplasia." (PMID 34884259, 2021). "CCL2, CCL7, and CCL8 expression was the highest in the hyperplastic polyps and lower in the adenomas, in which it gradually decreased along with an increasing villous component." (PMID 34884259, 2021).
allergic asthma (1 paper, 2022). A asthma with a basis in a pathological type I hypersensitivity reaction. "Moreover, Wnt-3a expression directly affects human mast cells to produce the chemokines IL-8 and CCL8 and can further promote the development of allergic asthma." (PMID 36463267, 2022).
Allergy (1 paper, 2015). An allergy is an immune response or reaction to substances that are usually not harmful. "The expression of Ccl8, known to attract actors of allergy and inflammation, was elevated in both Spink5-/- and Spink5-/-Klk5-/- skin, whereas Ccl20, a chemoattractant for CCR6+ cells including dendritic cells and Th17 cells, showed a significant increase only in Spink5-/- skin." (PMID 26390218, 2015).
aortic aneurysm (1 paper, 2009). A ruptured aneurysm located in the wall of the proximal portion of the descending aorta proceeding from the arch of the aorta. "Initially we confirmed the up-regulation of Il6, Ccl4, Ccl8 and MMP2 within aortic aneurysms using real time PCR." (PMID 19580648, 2009).
arteriosclerosis (1 paper, 2025). A vascular disorder characterized by thickening and hardening of the walls of the arteries. "Studies have demonstrated that inflammatory mediators such as fractalkine/CX3CL1, CCL8, M-CSF, HGF, E-selectin, PI3/elafin, CCL17, and IL-16 are significantly elevated in patients with AD, contributing to the progression of arteriosclerosis." (PMID 40757030, 2025).
atopic dermatitis (1 paper, 2014). "A number of chemokines [CCL2, CCL3, CLL4, CCL8, CCL13, CCL19, chemokine (C-X-C motif) ligand (CXCL) 1, CXCL6, CXCL16] were upregulated in sensitized dogs after allergen challenge, similar to what is observed in human atopic dermatitis." (PMID 25098772, 2014).
autoimmune disease (1 paper, 2023). A disorder resulting from loss of function or tissue destruction of an organ or multiple organs, arising from humoral or cellular immune responses of the individual to their own tissue constituents. "Furthermore, serum levels of CCL8, CXCL13, and IL-1RA were also higher in patients with SLE compared with patients with other autoimmune diseases and were moderately correlated with global SLE disease activity." (PMID 38098483, 2023).
bladder cancer (1 paper, 2025). "Conversely, high levels of other chemokines like CCL5, CCL8, CCL13, and CCL18 have been correlated with improved outcomes in bladder cancer patients." (PMID 39964621, 2025).
bladder tumors (1 paper, 2022). "Comparison of chemoattractants expression during MB49 bladder tumors grow highlighted CCL8 and CCL12 (CCR2-ligands), CCL9 and CCL6 (CCR-1-ligands), CXCL2 and CXCL5 (CXCR2-ligands), CXCL12 (CXCR4-ligand) and antagonist of C5/C5a as potential targets to decrease myeloid suppressive cells." (PMID 36613562, 2022).
brain injury (1 paper, 2024). Acute and chronic (see also brain INJURIES, CHRONIC) injuries to the brain, including the cerebral hemispheres, CEREBELLUM, and brain STEM. "In transient insult-induced brain injury, microglia drive the infiltration and clonal expansion of CD8+ T lymphocytes via CCL2/CCL8 chemokines." (PMID 38914581, 2024).
Cerebral ischemia (1 paper, 2024). Restriction of arterial blood supply to the brain associated with insufficient oxygenation to support the metabolic requirements of the tissue. "In cerebral ischemia models, CCL8 derived from microglial cells contributes to infarct progression by mediating CCR2/CCR5 CD8 T cell infiltration." (PMID 39475897, 2024).
Cirrhosis (1 paper, 2025). A chronic disorder of the liver in which liver tissue becomes scarred and is partially replaced by regenerative nodules and fibrotic tissue resulting in loss of liver function. "Patients with HCC with high scores had lower levels of interferon-gamma and CCL8 (false discovery rate <0.05), whereas patients with cirrhosis with high scores showed higher matrix metallopeptidase 2 (MMP2) levels (false discovery rate <0.05)." (PMID 40995436, 2025).
colorectal adenoma (1 paper, 2021). An adenoma that arises from the colon or rectum. "Therefore, to verify the effect of the polyp sublocation on chemokine expression and discern the independent predictors of CCL2, CCL7, and CCL8 expression in colorectal adenomas, a multivariate analysis was conducted." (PMID 34884259, 2021).
Colorectal polyps (1 paper, 2021). "Colorectal polyps are characterized by a significantly higher content of MCP-1, MCP-2, and MCP-3 proteins but a lower number of the respective CCL2, CCL7, and CCL8 transcripts, the downregulation of which is more pronounced in polyps with greater potential for malignancy." (PMID 34884259, 2021).
depression (1 paper, 2025). "Together, these findings indicate that aberrant expression of neuronal CCL8 plays an important role in phagocyte apposition and that inhibition of CCL8 expression may be responsible for the ability of MSCT to prevent synapse elimination and alleviate depression in patients with SLE." (PMID 40048256, 2025).
diabetic eye disease (1 paper, 2024). A group of disorders affecting the eye in patients with diabetes mellitus. "Concentrations of CCL8, CCL2, CXCL8 and CXCL10 may be associated with diabetic eye disease, especially in diabetic retinopathy and diabetic macular edema." (PMID 38790059, 2024). "Network meta-analysis revealed that CCL8, CCL2, CXCL8 and CXCL10 may be involved in key pathophysiological process of diabetic eye disease." (PMID 38790059, 2024). "Specifically, this network meta-analysis indicated that CC chemokines (CCL8 and CCL2) and CXC chemokines (CXCL8 and CXCL10) may discriminate between those with and without diabetic eye disease." (PMID 38790059, 2024).
diabetic neuropathy (1 paper, 2024). A chronic, pathological complication associated with diabetes mellitus, where nerve damages are incurred due to diabetic microvascular injury involving small blood vessels that supply these nerves, resulting in peripheral and/or autonomic nerve dysfunction. "Additionally, it has been shown that CCR5, CCL2, CCL3, CCL5, CCL7, CCL8, and CCL12 spinal mRNA and/or protein levels are elevated in rodent models of diabetic neuropathy, with some displaying sex-related diversity." (PMID 39457105, 2024).
endocrine cancers (1 paper, 2025). "Notably, endocrine cancers displayed the highest frequency of positive correlations with pro-inflammatory chemokine genes, particularly with CCL8, CCL11, CXCL1, CXCL5, and CXCL6, thus indicating a distinct regulatory pattern in this cancer subtype." (PMID 40806276, 2025).
enteritis (1 paper, 2024). Inflammation of the small intestine. "For example, CD169+ macrophages in the colon can secrete CCL8, attracting monocytes that promote the occurrence and development of enteritis in a model of enteritis induced by dextran sodium sulfate (DSS)." (PMID 39435598, 2024).
fibrosarcoma (1 paper, 2021). A malignant mesenchymal fibroblastic neoplasm affecting the soft tissue and bone. "Pharmacologic inhibition of one of the autocrine motility factors identified, Ccl8, significantly diminished both motility and invasiveness of the highly transformed fibrosarcoma cell." (PMID 34070472, 2021).
invasive candidiasis (1 paper, 2012). "In separate experiments, induction of Ccr1 and its ligands Ccl3, Ccl5, Ccl6, Ccl7, Ccl8 and Ccl9 by invasive candidiasis was examined in greater detail in mice injected with 1.25×105 CFU of C. albicans, which causes ∼80% mortality by day 14 post-infection." (PMID 22916017, 2012).
iron deficiency (1 paper, 2022). "In addition, F. nucleatum induced CCL8 expression in macrophages via the TLR4/NF-κB signaling pathway, which was inhibited by iron deficiency." (PMID 36136589, 2022).
kidney damage (1 paper, 2022). "We now show that in experimental NTS nephritis, JQ1 decreased kidney Grem-1 and Ccl8 expression, and this was associated to milder macrophage cell infiltration and the amelioration of kidney damage, therefore supporting their potential use as biomarkers of disease progression." (PMID 35215234, 2022).
leptospirosis (1 paper, 2024). A contagious bacterial infection caused by spirochetes of the genus Leptospira. "In previous studies, we have shown that CCL2, CXCL5, and CCL8 are involved in the leptospirosis process, although the mechanisms are not understood." (PMID 39534703, 2024).